TLR2 (toll like receptor 2)
Diseases named in the same sentence as TLR2 in open-access papers (continued):
Sharing a sentence is not in itself a finding about the gene and the disease.
tumor (continued). "In this study, we aimed to evaluate the therapeutic potential of the novel TLR2 agonist in B16F10 tumor-bearing mice." (PMID 41291775, 2025). "Another important TLR, expressed on myeloid cells and neoplastic cells, the TLR2 mediates the recognition of harmful molecules, leading to inflammation and activation of the MyD88/NF‐κB signaling pathway, which promotes tumor cell proliferation and survival." (PMID 40922674, 2025). "Different approaches have been proposed to target TLR2, whose dual role can mediate both anti-tumor immunity and pro-tumorigenic signaling." (PMID 41375047, 2025). "Meanwhile, TLR2 modulates immune responses and inflammation, influencing both tumor growth and the crosstalk between cancer and immune cells." (PMID 41375047, 2025). "This can activate TLR2 signaling in tumor cells, leading to the development of a chemotherapy-resistant phenotype, and it has previously been shown that TLR2 and HMGB1 have an important role in the self-renewal of breast CSCs." (PMID 40647457, 2025). "Recent studies have found that HSP70 secreted by tumor cells can bind to TLR2 on the surface of macrophages, forming an HSP70-TLR2 complex, which upregulates MerTK expression and promotes the polarization of macrophages to the M2 type." (PMID 40297581, 2025). "In HCC, gut microbial metabolites, including lipoteichoic acid (LTA) and DCA, upregulate cyclooxygenase-2 (COX-2) expression via toll-like receptor 2 (TLR2) on the membrane surface of tumor cells, which increases prostaglandin E2 (PGE2) expression." (PMID 40066456, 2025). "SUP3 exhibited stronger inhibition of tumor growth and metastasis than classical TLR2 agonist, Pam3." (PMID 41291775, 2025). "Among the various TLRs involved in GBM, TLR2 has been identified as a key mediator in modulating the tumor microenvironment." (PMID 40727443, 2025). "In this way, TLR2/NF-κB signaling establishes a molecular bridge between inflammatory cues and antioxidant/redox programs, enabling tumor cells to resist ferroptosis and oxidative stress." (PMID 41375047, 2025). "Radiation‐induced HMGB1 release drives tumor cell dedifferentiation into a stem cell phenotype via the TLR2/YAP/HIF‐1α signaling pathway, thereby accelerating tumor recurrence and metastasis." (PMID 41354099, 2025). "Tumor-derived exosomes hijack TLR2/NF-κB signaling in macrophages, suppressing OXPHOS and increasing lactate production, which drives PD-L1 expression and immunosuppression." (PMID 40562870, 2025). "Subsequently, scientists discovered that HMGB1, a natural activator of TLR2, with high mobility group box 1 secreted by tumor cells upon death." (PMID 40727443, 2025). "TLR2, through MyD88‐mediated signaling, can activate the NF‐κB pathway, resulting in increased pro‐inflammatory cytokine production, tumor cell proliferation, and survival." (PMID 40922674, 2025). "TLR2 drives the progression of chronic inflammation in CRC tumors, and the activation of NF‐κB can prevent tumor cell apoptosis and is associated with chemotherapy resistance." (PMID 40727252, 2025). "Following immune training with KK2DP7 and tumor inoculation, TLR2 and IRF7 were significantly activated in CD11b+ cells within the non‐lymphocyte layer of the mouse spleen, accompanied by a significant increase in interferon secretion." (PMID 40145812, 2025). "Tumor growth and intra-tumor M2 MΦs were significantly reduced upon cancer cell Hsp70 knockdown and in TLR2 knockout mice." (PMID 39941817, 2025). "Tumor-derived exosomes signal through TLR2 on infiltrating macrophages, drive NF-κB-dependent aerobic glycolysis in these cells, and up-regulate PD-L1, thereby polarizing macrophages toward an immunosuppressive phenotype within a pre-metastatic niche." (PMID 41465346, 2025).
tumor (continued). "With the demand for effective anti-tumor treatments, our results provide a compelling proof-of-concept of a TLR2 agonist for cancer immunotherapy." (PMID 41170411, 2025). "The NF-κB pathway triggered by eHSP70 binding to TLR2/4 on H22 hepatocellular carcinoma cells also has the potential to exhibit antiapoptotic properties that promote tumor growth." (PMID 39911383, 2025). "DC function is often suppressed by the tumor microenvironment, while current TLR2 agonists exhibit suboptimal stability and diminished efficacy in vivo." (PMID 41291775, 2025). "The expression of TLR2 was also increased after poly (I:C) treatment compared to adherent cells and tumor spheres." (PMID 40647457, 2025). "NF-κB activation triggered two distinct pathways that enhanced glycolysis in response to TLR2/MyD88 signaling after tumor-derived exosome ligation." (PMID 40443670, 2025). "Tumor-derived exosomes activate the toll-like receptor 2 (TLR2)/NF-κβ signaling axis in macrophages, driving HIF-1α-mediated upregulation of GLUT-1." (PMID 41463352, 2025). "This duality of functions makes TLR2 a “two‐faced factor” in which its activation can both facilitate defense against cancer and promote tumor progression." (PMID 40922674, 2025). "After tumor - derived exosomal HSP70 binds to TLR2 on the surface of MDSCs, it activates STAT3 phosphorylation, induces the expression of arginase 1 (Arg1) and inducible nitric oxide synthase (iNOS), and enhances the immunosuppressive activity of MDSCs." (PMID 40297581, 2025). "Tumor growth in TLR2−/− mice was significantly slower compared to tumor growth in WT mice, and intra-tumor MΦs from TLR2−/− mice showed a significant reduction in M2 polarization compared to MΦs from WT mice." (PMID 39941817, 2025). "TLR2 IHC and histologic counterstaining in a section of pancreatic cancer tumor from a human patient and in a section of an SU.86.86 orthotopic xenograft have comparable patterns of TLR2-expressing tumor cells (brown stain) and infiltrated stroma (blue stain)." (PMID 39320054, 2024). "Nevertheless, TLR2 knockout significantly diminished the inhibitory effects of OVA-MITO/TRP2-MITO on tumor growth in both the prophylactic model and therapeutic model." (PMID 39164536, 2024). "The ability of tumor secretions to induce ARG1 is completely lost in neutrophils isolated from mice with TLR2 or MyD88 knockouts." (PMID 38523155, 2024). "SAPE‐OOH and toll‐like receptor 2 (TLR2) mediate macrophage phagocytosis of tumour cells to inhibit tumour progression." (PMID 38652105, 2024). "They discovered that LBB boosts intestinal mucosal epithelial barrier integrity and decreases tumor incidence by promoting epithelial cell apoptosis and inflammation through the TLR2 pathway in the host." (PMID 39175566, 2024). "All tumor samples from the in-house cohort were included, where the expression levels of TLR2 and genes related to T cell exhaustion were measured." (PMID 38769374, 2024). "Several observations concerning mitochondria, DCs, tumor vaccines, and the TLR2 pathway were made in the current study." (PMID 39164536, 2024). "Tumor-derived versican dampens DC function by binding to TLR2 and forming a positive feedback loop characterized by the upregulation of IL-10/IL-6 receptors, resulting in tumor immunosuppression." (PMID 38946426, 2024). "TLR-4 and TLR-2 have shown superior tumor antigen recognition patterns and the capacity to trigger innate and acquired immune responses in the ten types of TLRs (Toll-like receptors)." (PMID 39050853, 2024). "Knockout of TLR2 in mice dramatically diminished the tumor inhibitory effects of OVA-MITO as a prophylactic tumor vaccine." (PMID 39164536, 2024). "Fluorescent liposomes (rhdamined orid-liposome or TLR2 pep-orid-liposome) were intravenously administered into tumor-bearing Balb/c nude mice, which had been intraperitoneally inoculated with HL60 cells." (PMID 38812031, 2024).
tumor (continued). "For instance, TLR2-depleted spherical mammospheres cells only gave rise to tumor growth in 5 out of 14 mice, in contrast to control cells, which developed rapidly growing tumors in all mice." (PMID 38347830, 2024). "Literature data indicate that increased expression of TLRs, particularly TLR2, TLR4, and TLR9, in tumor cells and the tumor microenvironment is associated with GC progression." (PMID 39451226, 2024). "In a melanoma tumor model, TLR2 agonists specifically stimulate macrophage polarization toward the M1 phenotype." (PMID 39403370, 2024). "Upon activation, TLR2 initiates a cascade of anti-tumor mechanisms, including cytokine production and the activation of immune cells, particularly promoting macrophage differentiation towards the M1 phenotype." (PMID 38903515, 2024). "Biglycan is upregulated in tumor endothelial cells of metastatic tumors, facilitating the migration of toll-like receptor 2/4+tumor cells, which increases circulating tumor cells and lung metastasis." (PMID 38576482, 2024). "TLR2, an upstream signaling molecule of MyD88, depletion impedes the tumor-initiating capacity of cells." (PMID 38347830, 2024). "Concerning the LTA/TLR-2/COX-2 pathway, it promotes the activation of prostaglandin E2 (PGE2) in HSCs, which is associated with a reduced anti-tumor response in the TME." (PMID 39064815, 2024). "In contrast, tumor cells often exhibit overexpression of specific TLRs, such as TLR2, TLR4, and TLR9." (PMID 39640496, 2024). "The bio-distribution of orid-liposome or TLR2 pep-orid-liposome in various organs and tumor was quantitatively evaluated at three distinct time points (12, 24, and 48 h post-injection) by an in vivo optical imaging system (Mean ± SD, n = 3)." (PMID 38812031, 2024). "Tumor-derived exosomes activate NF-κB through Toll-like receptor-2 (TLR2), leading to the upregulation of PD-L1 expression." (PMID 38655063, 2024). "In preclinical tumor models, intratumoral injection of a TLR2 agonist or targeted delivery of nanoparticles loaded with a TLR7/8 agonist have also been demonstrated to induce repolarization of TAMs towards an anti-tumor phenotype." (PMID 39596395, 2024). "Ligation of TLR2 by versican has been reported to activate stromal cell populations in tumor microenvironment and subsequent inflammatory cytokine secretion." (PMID 37784035, 2023). "Certain tumor-derived exosomes contain heat shock protein 72 (Hsp72) in their membrane and interact with Toll-like receptor 2 (TLR2) on MDSCs, thereby activating cells." (PMID 37258584, 2023). "When activated, TLR2 can either promote or hinder tumor growth, depending on the specific immune cells involved." (PMID 38203626, 2023). "IL-11 promoted tumor progression by initiating gp130/Stat3 pathway through TLR2, and cancer metastasis was inhibited by blocking the TLR2 signal in mice." (PMID 37153547, 2023). "The abundance of B. adolescentis was correlated with the number of Decorin+ macrophages and the expression level of TLR2 in tumor tissue of CRC patients." (PMID 37464382, 2023). "HMGB1 has been found to be secreted from tumor cells, which also mediated anti-tumor immune responses via activating Toll-like receptor 2 + 4 signaling." (PMID 37174080, 2023). "Upregulation of TLR2 can promote gastric tumorigenesis independently of tumor inflammation, while its knockdown has been shown to inhibit the proliferation of CRC tumors." (PMID 37112730, 2023). "The HMGB1 released from the necrotic tumor executes alarmin functions, activating tumor growth signaling via binding to a variety of receptors including TLR2/4, RAGE, and C-X-C motif chemokine receptor 4 (CXCR-4)." (PMID 37210579, 2023). "Activation of Toll-like receptors (TLRs) promotes anti-tumor immunity and is used in cancer therapy: agonists for TLR2/4, TLR4, and TLR7 were approved by the FDA." (PMID 37189417, 2023).
tumor (continued). "Prior studies suggested that TLR2/YAP axis played an important role in innate immunity and the activation of TLR2/YAP axis in tumor cells suppressed tumor growth." (PMID 37464382, 2023). "ICD-related gene toll-like receptor 2 (TLR2), a regulator of oncogene-induced senescence, is an important tumor suppressor in premalignancy." (PMID 37968457, 2023). "It was demonstrated that the TLR2/6 agonists (Pam2CAG and Pam2CGD) were more efficient than the TLR2/1 agonist (Pam3CAG) for the therapeutic anti-tumor vaccination." (PMID 38258035, 2023). "The authors showed that HMGB1 is an endogenous agonist for TLR2, which is released from dying tumor cells in response to radiation or other stress-inducing agents (e.g., temozolomide)." (PMID 37112730, 2023). "The naïve cohorts of CC-LR/TLR2, 4, and 9 mice also showed 1.7-fold (35 vs 60), 1.5-fold (40 vs. 60), and 2-fold (30 vs. 60) reductions in tumor numbers respectively compared to age and sex match naïve CC-LR mice." (PMID 37283745, 2023). "TLR2 plays a role in the regulation of CSCs, a subpopulation of tumor cells with self-renewal and tumor-initiating capabilities." (PMID 38203626, 2023). "Consistently, polysaccharides from Agaricus blazei Murill stimulated MDSC differentiation from M2 to M1 type, which mediates inhibition of tumor immune evasion via the Toll-like receptor 2 (TLR2)." (PMID 36969071, 2023). "TLR2 is expressed over the keratinocytes in oral squamous cell carcinoma and this receptor particularly regulates the growth and survivability of the tumor cells by promoting the immune-escape and inhibition of apoptosis." (PMID 37822929, 2023). "Collectively, PepO provoked M2 macrophages to polarize toward the anti-tumor M1 phenotype, which was dependent on both TLR2 and TLR4." (PMID 37925462, 2023). "Macrophage-activating lipopeptide-2 (MALP-2), a TLR2/6 agonist, enhances NK cell cytotoxicity towards the tumor cells, while the PGE2 mediated immunosuppression was blocked by COX-2 inhibitor." (PMID 37936697, 2023). "The smectite carrying probiotic biofilm was able to activate dendritic cells via TLR2 signaling in a mouse model and inhibit tumor growth." (PMID 37740010, 2023). "In vitro experiments demonstrated that BGN promoted tumor progression and transformation of MCs into CAFLCs by TLR2/TLR4/NF-κB signaling pathway." (PMID 36632455, 2023). "Exosomes derived from prostate cancer cells can upregulate CXC motif receptor 4 (CXCR4) via the TLR2/NF-κB signaling pathway, eventually promoting the migration of MDSCs into the tumor microenvironment in a CXCR4–CXCL12 axis-dependent manner." (PMID 36911674, 2023). "The macrophages in the invasive zone exhibited an M2-like phenotype with increased expression of CD163, MRC1, and SAAs receptor TLR2, whereas macrophages in the tumor tissue exhibited features of ECM remodeling and increased expression of MMP9 and MMP14." (PMID 37337030, 2023). "Activation of TLR2 enhanced anti-tumor CD8 T cell responses and boosted the efficacy of PD-1/PD-L1 blockade in murine melanoma." (PMID 37189417, 2023). "Conversely, TLR2−/− mice treated with AOM-DSS have been shown to have an increased tumor incidence with rampant proliferation and dampened apoptosis, although TLR2 deletion under normal conditions shows a reduced proliferation and increased apoptosis in IECs." (PMID 37519301, 2023). "Both in vitro and in vivo experiments demonstrated that BGN promoted tumor progression and transformation of MCs into CAFLCs through the TLR2/TLR4/NF-κB signaling pathway." (PMID 36632455, 2023). "A detailed analysis of the percentage of peripheral blood lymphocytes expressing TLR2 showed a statistically significant increase in the observed values with increasing tumor stages advancement." (PMID 36982898, 2023). "TLR2 polarizes the TAMs to a pro-tumor M2 phenotype in HCC cells, and promotes the proliferation of HCC." (PMID 37020586, 2023).
tumor (continued). "The expression of TLR2 marks the activation of immunity, and L-pampo, as a TLR2 agonist, induces apoptosis and immunogenic tumor cell death by mediating the activation of Th1 and Th252." (PMID 37666853, 2023). "Given their complexity roles in tumor immunity as either pro-tumor, anti-tumor, or dual effects, several TLRs (i.e., TLR2, 3, 4, 5, 7, and 9) have been reported to be dysregulated in human GC cells." (PMID 37822929, 2023). "In this context, HMGB1 expressed on the surface of tumor-derived EVs can interact with TLR-2 on B cells, inducing the expression of T cell Immunoglobulin and Mucin domain 1 (TIM-1) on B cells via an MAPK-pathway-dependent mechanism." (PMID 37175226, 2023). "Anti-tumor effect of MIP through the TLR2-MyD88 axis has been well elucidated whereas the TLR9- MyD88 axis has not been studied yet." (PMID 37122749, 2023). "Shock protein 70 (HSP70) on the membrane of tumor-derived EVs can activate MDSC by interacting with toll-like receptor 2 (TLR2)." (PMID 35915054, 2022). "From the immune perspective, VCAN has been credited with immunoregulatory functions: it acts through Toll-like receptor 2 (TLR2) to dampen antigen presentation by tumor-infiltrating dendritic cells." (PMID 36371231, 2022). "Signaling analysis of the tumor-derived versican-mediated TLR2 signaling identified TLR6 as necessary heterodimer and MyD88 as responsible TLR adapter." (PMID 36224342, 2022). "Metabolites of gut microbiota including lipoteichoic acid (LTA) and deoxycholic acid upregulate cyclooxygenase-2 (COX2) expression through toll-like receptor 2 (TLR2) on tumor cell membranes." (PMID 36358736, 2022). "To do this, we performed immunohistochemistry (IHC) staining for TLR2 on surgically resected early-stage human LUAD specimens and found that TLR2 expression is significantly increased in LUAD tumor epithelium in comparison with adjacent normal epithelium." (PMID 36351380, 2022). "In this report, we study the role of Toll-like receptor 2 (TLR2), a regulator of oncogene-induced senescence, which is a key tumor suppressor response in premalignancy." (PMID 36351380, 2022). "A recent study showed that HMGB1 acted as a ligand for toll-like receptor 2 (TLR2) on bone marrow-derived GB-infiltrating dendritic cells to elicit tumor regression." (PMID 35193644, 2022). "Immune and stromal cell populations included 2 populations: Macrophages 1 (c1: C1qa, C1qb, C3aR1, Cd68, Csf1r, Tlr2, and Cd86) and 2 (c6 + c9: Ccr7, Csf2rb, Il1b, and Cd74) expanded in PNs as a percentage of total tumor cells." (PMID 36134665, 2022). "Colon carcinogenesis has been associated with increased expression levels of TLR2 and TLR4, which are targets for tumour treatment." (PMID 36433652, 2022). "GM-CSF production seems to have a synergistic effect with Toll-Like Receptor—2 (TLR2) to inhibit tumor growth and modulate tumor-infiltrating Antigen Presenting Cells (APCs), and IL-18 has been associated with better survival rates in cancer patients." (PMID 36296703, 2022). "KrasLSL–G12D/+ mice on a Tlr2−/− background (KrasLSL-G12D/+;Tlr2−/−) developed more tumors and had a significantly increased tumor burden compared with controls (KrasLSL-G12D/+;Tlr2+/+)." (PMID 36351380, 2022). "A similar TLR2/4-STAT3 response driven by HSPs was seen in bone marrow-derived dendritic cells (BMDCs) promoting a pro-tumor IL-6, PGE-2, IL-1, and TNF response after exosome treatment." (PMID 35320943, 2022). "In CD8+ cells isolated from peripheral blood of tumor patients, the TLR2 agonist Pam3Csk4 enhanced the cytolytic activation of peripheral and tumor-infiltrating CD8+ T cells from GCs." (PMID 36341377, 2022). "OPN-301, an inhibitory anti-TLR2 antibody, suppressed tumor initiation and growth in a gastric animal model, which was associated with gene suppression of CXCL2 and TNF-α." (PMID 36479129, 2022). "Taken together, these data suggest that TLR2 regulates a proinflammatory SASP in NSCLC correlating with impairment of tumor progression." (PMID 36351380, 2022).